TMEM167A (transmembrane protein 167A)
Description:
Involved in the early part of the secretory pathway.
Synonyms: TMEM167; FLJ30508; MGC23909; kish
Tractability: Antibody: UniProt predicts a signal peptide or a membrane-spanning region. PROTAC: ubiquitination databases record sites on it; its protein half-life has been measured.
Gene: Protein-coding gene on chromosome 5 (83,052,846 to 83,077,863, reverse strand). Ensembl gene ENSG00000174695.
Subcellular location: Golgi apparatus membrane
Subcellular location (Human Protein Atlas): Vesicles
Gene Ontology:
Molecular function: protein binding
Biological process: constitutive secretory pathway; protein secretion
Cellular component: Golgi apparatus; Golgi membrane
Genetic constraint (gnomAD): Loss-of-function variants: 4 observed, 5.49 expected, observed/expected ratio (o/e) 0.73, 90% interval 0.36 to 1.59. That is too few expected variants to judge how well the gene tolerates losing a copy. Missense variants: 45 observed, 62.9 expected, observed/expected ratio (o/e) 0.72, 90% interval 0.56 to 0.92. Synonymous variants: 17 observed, 22.58 expected, observed/expected ratio (o/e) 0.75, 90% interval 0.51 to 1.13.
Homologues: Orthologues: chimpanzee TMEM167A (100% identical), macaque TMEM167A (100% identical), dog TMEM167A (99% identical), pig TMEM167A (99% identical), mouse Tmem167 (97% identical), rat Tmem167a (96% identical), guinea pig TMEM167A (93% identical), zebrafish tmem167a (90% identical), tropical clawed frog tmem167a (88% identical), rat AC242615.2 (76% identical), Drosophila melanogaster ksh (72% identical), Caenorhabditis elegans popl-7 (71% identical). Paralogues in human: TMEM167B (43% identical).
Diseases named in the same sentence as TMEM167A in open-access papers:
TMEM167A is named in the same sentence as 11 diseases in open-access papers, as found by Europe PMC text mining. Sharing a sentence is not in itself a finding about the gene and the disease. The quoted sentences say what the papers report.
glioma (2 papers, 2020 to 2022). A benign or malignant brain and spinal cord tumor that arises from glial cells (astrocytes, oligodendrocytes, ependymal cells). "In agreement with the effect observed after TMEM167A downregulation in gliomas cells, it has been shown that RAB7 is essential for AKT activation and signaling in other cancer cells." (PMID 31947645, 2020). "Little is known about TMEM167A, but it has prognostic significance in lung cancer and glioma." (PMID 36010951, 2022). "We focused on TMEM167A, as we had previously linked this gene to EGFR regulation in gliomas." (PMID 31947645, 2020). "Although we have previously observed that the growth of most of the lines used in this study is EGFR-dependent, we cannot discard that TMEM167A might be necessary for the trafficking and/or the signaling of other receptors present in gliomas." (PMID 31947645, 2020). "We chose the three genes most significantly enriched in the high-EGFR gliomas: GOSR1, TMEM167A, and STX17." (PMID 31947645, 2020). "In summary, our results demonstrate that TMEM167A is essential for the function of acidic vesicles, which are necessary for the maintenance of the EGFR–AKT axis in glioma cells." (PMID 31947645, 2020). "Overall, our results highlight the relevance of the endomembrane system regulation by TMEM167A in EGFR-dependent gliomas, because it controls a key step in the development of aggressive glioma, where EGFR signaling and autophagy maintenance converge." (PMID 31947645, 2020). "However, our results indicate that the function of TMEM167A is independent of the PTEN status, as this gene is lost in both responsive (U87) and nonresponsive (U373) glioma cells." (PMID 31947645, 2020).
breast carcinoma (1 paper, 2024). "Comparative analysis with the well-established MCF-10A reference cell line revealed a significant upregulation of APOA5, CHAC1, EMID1, GOSR2, TCP1, and TMEM167A in breast cancer cell lines." (PMID 38300336, 2024).
diabetes (1 paper, 2025). "To gain insights into the mechanisms leading to diabetes, we silenced TMEM167A in EndoC-βH1 cells and knocked-in one patient’s variant, p.Val59Glu, in induced pluripotent stem cells (iPSCs)." (PMID 40924476, 2025). "Identification of further individuals with TMEM167A variants will be essential to establish whether a variable diabetes phenotype is observed with this MEDS subtype." (PMID 40924476, 2025).
epilepsy (1 paper, 2025). A brain disorder characterized by episodes of abnormally increased neuronal discharge resulting in transient episodes of sensory or motor neurological dysfunction, or psychic dysfunction. "Our study identifies variants in TMEM167A as a genetic cause of MEDS, a congenital syndrome characterized by microcephaly, epilepsy, and neonatal diabetes." (PMID 40924476, 2025).
glioblastoma (1 paper, 2024). The most malignant astrocytic tumor (WHO grade IV).
Lissencephaly (1 paper, 2025). A spectrum of malformations of cortical development caused by insufficient neuronal migration that subsumes the terms agyria, pachygyria and subcortical band heterotopia. "Further studies will be needed to confirm whether lissencephaly is a common clinical feature of MEDS caused by TMEM167A variants and to define the molecular mechanism." (PMID 40924476, 2025).
microcephaly (1 paper, 2025). A congenital or acquired developmental disorder in which the circumference of the head is smaller than normal for the person's age and sex. "We discovered TMEM167A variants as a cause of neonatal diabetes and microcephaly." (PMID 40924476, 2025). "We recommend inclusion of TMEM167A in gene panels used for genetic testing of neonatal diabetes and congenital microcephaly." (PMID 40924476, 2025).
tumor (1 paper, 2020). "However, the data presented here indicates that the activation of AKT activation and the orthotopic tumor growth of GBM cells carrying the EGFRvIII mutation are also sensitive to TMEM167A downregulation." (PMID 31947645, 2020). "Moreover, we found that TMEM167A inhibition in this subgroup of GBMs reduced the EGFR–AKT signaling axis and impaired tumor growth." (PMID 31947645, 2020).
TMEM167A also shares sentences with these, for which no sentence is quoted: cancer (1 paper); epilepsy syndrome (1); lung carcinoma (1).